CD163 (CD163 molecule)
Diseases named in the same sentence as CD163 in open-access papers (continued):
Sharing a sentence is not in itself a finding about the gene and the disease.
tumor (continued). "The amounts of M2 (CD163+) and M1 (CD86+) macrophages showed individual variation in the tumor microenvironment." (PMID 32444799, 2020). "Tumor-infiltrating macrophages have been classified as M1 (antitumor) or M2 (protumor) according to the co-expression of CD68, iNOS or MRC1/CD206, CD163, Arg1, and other markers in in vitro models." (PMID 32168749, 2020). "Tumor biopsies with high tumor vascular ANGPT2 expression showed an increase in CD68+ and CD163+ macrophages after Ipilimumab or Ipi-bev treatment." (PMID 32793228, 2020). "The mean number of tumor-infiltrating CD4+, CD8+, and CD163+ cells was 142 (range 2-580), 113 (range 1-540), and 170 (range 3-624) per high-power field, respectively." (PMID 33457428, 2020). "In growing cancer, TAMs express peculiar surface molecules, including CD163 and CD206, and display features related to angiogenesis, lympho-angiogenesis and tissue remodeling, thus favoring tumor progression and metastasis formation." (PMID 32650452, 2020). "Immunohistochemical staining of the tumor using immune markers such as PD1, PDL1, CD163, CD3, and CD8 showed heterogeneity depending on the regions within the tumor." (PMID 33297519, 2020). "In this study, we assess the prognostic significance of macrophage subpopulation densities and their ratios (CD68+, CD163+, and CD68+CD163− expressing cells) within different regions of the tumor (IM, CT, IMCT) using automated image analysis." (PMID 32435699, 2020). "When CD14+ monocytes engulf tumor-derived miR-21-containing exosomes, they display increased expression of M2-like markers (CD206, CD163, IL-10) and down-regulation of M1-like markers (IL-18, IL-12B, HLA-DR)." (PMID 32486098, 2020). "We found that in the tumor and the tumor microenvironment, CCL2 and CXCL10 localized in Nestin+, Iba-1+, CD16+ and CD163+ cells." (PMID 32943658, 2020). "Multiplex immunofluorescent staining of tumor samples from NSCLC Swedish patients demonstrated the co-localization of CD68, CD163, and MARCO." (PMID 33194645, 2020). "M2 TAMs express CD163, CD115, and CD206; they are able to secrete IL-10, promote tumor growth, and foster angiogenesis." (PMID 32532153, 2020). "Multiplex immunofluorescence staining was performed to quantify CD163, HLA-DRA and CD14 expression in the tumour area annotated by AMACR staining." (PMID 32908142, 2020). "To further support the notion that the CD163-labelled M2 macrophages were activated, we showed expression of IL-10, TNF-α, TGF-β1 and IL-6 in all tumour tissues." (PMID 32070062, 2020). "Here, we selected tumor immunity-related biological markers, including CD8, FOXP3, and CD163, which, respectively, represented CD8+ T cells, FOXP3+ Treg cells, and CD163+ M2 macrophages to analyze different advanced GC types." (PMID 32983971, 2020). "We also found an increased infiltration of TAMs immunostained with anti-CD163 and anti-CD206 antibodies in tumor originated from LNCaP cells stably transfected with SFMBT2 shRNA." (PMID 32971847, 2020). "When macrophages were activated by infection and tumor, the expression of CD163 molecules on macrophage membrane was increased, and the content of sCD163 in serum was increased." (PMID 31915467, 2019). "Tumor cell mitoses, CD68+ or CD163+ macrophages, CD47, calreticulin, or checkpoint molecules were not significantly different in these two groups." (PMID 30938231, 2019). "To understand the relationship among CD47, PD-L1, and TAM in PDAC, we stained the tumor specimen from 106 PDAC patients with anti-CD47, anti-PD-L1, anti-CD68, and anti-CD163 antibodies." (PMID 31771616, 2019). "The 48 h coculture initiates a pro-tumor phenotype skewing of MΦ, indicated by downregulation of IL1B, IL12, CCL18, CD80, as well as CD163, and upregulation of CLEC7A (dectin-1), CD86, CD206, and HLA-DR." (PMID 30850595, 2019).
tumor (continued). "Similarly, CD163 stainings demonstrated a progressive increase of tumor-associated macrophages (TAMs) in the surrounding primary tumor stroma, with 4T1 primary tumors showing significantly higher CD163 positivity at 1 and 3 w p.i., but not at 6 w p.i. compared to Py230 primary tumors." (PMID 31921184, 2019). "Namely, the presence of tumor infiltrating CD3+CD8+FoxP3− T cells, galectin-9+ dendritic cells (DC)/DC-like macrophages, a high CD14+CD163− (M1)/CD14+CD163+ (M2) macrophage ratio, and the expression of galectin-3 by tumor cells." (PMID 31248118, 2019). "Observation of CD3+CD8+ T lymphocyte and HLA‐DRA+CD163+ macrophage infiltration in these tumors, and demonstration of GBP1 expression in tumor cells also attested to the activation of this pathway." (PMID 31025552, 2019). "PD-L1 expression on ICs and tumor cells, ICs by H&E, CD8+ T cells, and CD163+ macrophages was evaluated using IHC." (PMID 31647026, 2019). "Surprisingly, the CD68+CD163+CD206+ macrophages, expressing both M2-like markers, were abundant in the tumor regions but were consistently located furthest from the tumor cells." (PMID 31477692, 2019). "The CD163+ and CD68+CD206+ macrophages were found to continuously upregulate PDL1 as they became more embedded in the tumor-nest." (PMID 31477692, 2019). "These images have been analyzed in full analogy to the tumor subsections, obtaining counts and densities for CD14- and CD163-positive macrophages, to be investigated for possible correlations with the documented clinical outcome." (PMID 31303867, 2019). "However, at tumor stroma neither CD163 nor CD68 expression was associated with the EMT program." (PMID 30927925, 2019). "The CD68+, CD68+CD206++ and CD68+CD163+CD206+ macrophages were abundant in all ROI but given their dominant presence in the adjacent normal tissue (white circle), they could be associated with the normal-tissue macrophages more than tumor-associated macrophages." (PMID 31477692, 2019). "Our data show an inverse relationship between CD163 and CD206 expression on TAMs as they near the tumor cells." (PMID 31477692, 2019). "Tumor tissue lysates of the CT26Flag−CAGE1 cells showed higher expression of autophagic flux, tryptase, chymase, and CD163 but lower expression of iNOS than CT26 tumor tissue lysates." (PMID 31799196, 2019). "Because SR-A is a marker of differentiated macrophages, we compared the expression pattern of CD68, CD163, CD14 and SR-A in CHL tumor microenvironment." (PMID 31714922, 2019). "Using immunohistochemistry, tumor tissues were stained with antibodies against CD3, CD8, CD163, iNOS, Forkhead box P3 (FOXP3), and CD33." (PMID 30729718, 2019). "Irrespective of the mechanism, B lymphocyte function appeared to be attenuated in a tumor microenvironment rich in IL-10 or PTGS2, coding for COX-2, or to a lesser extent also CD163." (PMID 30879106, 2019). "This was confirmed in the current set of 43 tumours, by determining the numbers of lymphocytes (CD3+, CD4+, CD8+, FoxP3+; using immunofluorescence (IF)) and macrophages (CD68+, CD163+, CD68+CD163+; using IF)." (PMID 31337000, 2019). "We also examined macrophage presence in HNSCC tumor tissue using CD68 (pan-macrophage marker), iNOS (M1 marker) and CD163 (M2 marker)." (PMID 31379843, 2019). "These iron-positive macrophages (iTAMs) are hallmarked by low expression of the iron exporter ferroportin and positivity for CD86, CD163, and HMOX1 as well as a pro-inflammatory phenotype with the ability to kill tumor cells." (PMID 31383898, 2019). "By immunohistochemical analysis, in tumor tissue, the median level of CD68 + cells/ HPF was 27 (range, 7–83), and the median level of CD163 + cells/HPF was 17 (range, 2–78)." (PMID 31694577, 2019). "In the tumor stroma, we observed heterogeneous pattern of claudin-2 expression in macrophages with the presence of CD68+/cl2−, CD68+/cl2+ (see Fig. 1D2), CD163+/cl2− and CD163+/cl2+ cells (see Supp Fig.3B1 and C)." (PMID 29134439, 2018).
tumor (continued). "In tumor resection specimens, the pan-macrophage marker CD68 showed a significant positive correlation with the other investigated macrophage markers (CD11c, CD163 and MRC1)." (PMID 30115022, 2018). "High tumor grade correlated with higher frequencies of CD3+, CD68+ CD163+ TAMs, and CD25+ FOXP3+ Treg cells, but Treg frequencies were significant predictors of favorable prognosis in patients with familial ovarian cancer (11/73 patients with BRCA mutation)." (PMID 30042343, 2018). "As expected, CD14+ cells in tumour tissue exhibited an M2-like alternative phenotype, as shown by their higher expression of CD64 and CD163 with respect to peritumours." (PMID 30285662, 2018). "Increased expression of KLRC1, CCL5, PLP1, CD163, MSR1, and GPNMB was found following treatment and tumor recurrence." (PMID 30151353, 2018). "The prognostic role of TAMs identified with CD163 on RFS was evaluated in 4 studies, of which 1 study assessed the correlation of RFS with CD163 detected in tumor stroma or islet, respectively." (PMID 29861872, 2018). "HE and IHC analysis of the CD68 and CD163 macrophage markers of pre-vaccine, post-chemotherapy FFPE tumor of Patient #3." (PMID 30326856, 2018). "CD68+ or CD163+ TAMs showed a uniform density in the tumor stroma, TCA, TIF and were also present in necrotic tumor regions." (PMID 30038715, 2018). "They possess an immunosuppressive M2 phenotype characterized by the expression of CD163, CD204, CD206, and IL-10, and their presence correlates with tumor progression." (PMID 30042343, 2018). "M2-TAMs, which induce a tumor-promoting microenvironment, are characterized by co-expression of CD68 and CD163." (PMID 30065206, 2018). "The xenograft tumor tissues of cancer cells and THP-1 derived TEM co-injection and patients’ tumor tissues showed that CD163-positive cells were also characterized as high Nrf2 nuclear-translocation." (PMID 30180849, 2018). "Breast G1/G2, G3 grade tumor and control specimens were immunostained for CD68, CD163, tryptase and CD31 to estimate total macrophages, M2-macrophages, mast cells, endothelial cells in the interstitial spaces and in periglandular position." (PMID 29854311, 2018). "Markers such as serum levels of CD163 (sCD163), the presence of CD68+ or CD163+ CD204+ macrophages in the tumor region can be used as indicator of macrophage or TAM activation following drug treatment." (PMID 30062558, 2018). "Accumulating evidence has suggested that not only a high frequency of CD163+CD68+ TAMs, but also a high amount of CD163 in serum or in tumor are correlated with a poor prognosis in patients with cancer." (PMID 29456539, 2018). "The percent positive pixels for CD163, CD8, and tumor marker expression by IF were comparable to chromogenic IHC with manufacturer’s recommended protocols (p>0.05)." (PMID 30400835, 2018). "Tumor tissue obtained at surgery was assessed for IDH1-R132H expression and CD163+ TAM infiltration by immunohistochemistry." (PMID 30400835, 2018). "We used a well-known pan TAM marker CD11b and a classical M2 TAM marker CD163 in fluorescence-activated cell sorting (FACS) to obtain the tumour-supportive M2 TAMs (CD11b+/CD163+) and the control TAMs (CD11b+/CD163−)." (PMID 28569747, 2017). "Tumor-infiltrating lymphocyte markers: CD3, CD4, CD8, CD20 and CD163 were evaluated using RNA-Seq data." (PMID 28537889, 2017). "Although M1 macrophages has anti-tumor function, our data shows markers including CD68, CD86, TLR2 and TLR4 are correlated with CD163 too." (PMID 29152078, 2017). "Taken together, these data indicate that cluster A TAMs are skewed towards alternative activation (CD163), extracellular matrix (ECM) remodeling (PCOLCE2) and promotion of tumor growth (IL-6)." (PMID 28327095, 2017). "PD-L1 expression was identified on tumor cells in five (19%) primary CM and on stromal cells (mainly CD68+CD163+ M2 macrophages) in 16 (59%) cases." (PMID 28903377, 2017).
tumor (continued). "The tumor stromal cells expressing α-SMA, CD68, CD163, and IL-6 were evaluated in B viral multistep hepatocarcinogenesis." (PMID 28114366, 2017). "Immunohistochemical staining revealed that tumor samples taken at baseline before treatment had variable numbers of CD3+ cells, CD8+ cells, CD4+ cells, CD68+ cells, CD163+ cells, and CD11c + cells." (PMID 26981247, 2016). "To further investigate the ability of AXL-expressing TNBC cells to promote macrophage polarization towards a pro-tumor phenotype, we analyzed the expression of the M2 specific markers CD206 and CD163 by flow cytometry." (PMID 28721387, 2016). "Here we showed that, when compared to HGSOC (n = 55), LGSOC patients (n = 25) exhibited lower density of tumor-infiltrating CD68+ macrophage, along with an attenuated M2-skewed (CD163+) phenotype." (PMID 27462782, 2016). "Immunohistochemical studies displayed that CD163, CD11c, Mac387 and CD68 (both KP1 and PGM clones) were diffusely positive, which verified that the neoplasm cells were of histiocytic origin." (PMID 27535029, 2016). "We therefore further examined different macrophage markers (M1; Nitric oxide synthase 2 (NOS2) and M2; CD163 and Heme oxygenase 1 (HMOX1)) in prostates injected with the different tumor EVs." (PMID 27550147, 2016). "The immune cells recruited to the tumor included cells expressing markers CD68, CD163, CD4, and CD25." (PMID 26964534, 2016). "A variety of markers (including CD68, CD163, CD204, HLA-DR, etc.)were used to identify different types of TAMs and the micro-distribution (in the tumor islet, stroma, or both) of TAMs in the tumor tissues." (PMID 27144518, 2016). "Our results fit this mechanism well, since we found that there is a positive correlation between CD163+ macrophages and MMP-9 tumor levels, as demonstrated by Spearman analysis." (PMID 27462782, 2016). "This is the first time showed that a fraction of OSCC tumor cells exhibited definite CD68 and CD163 expression." (PMID 26769084, 2016). "Double-staining immunohistochemistry of CD163/p-STAT, CD68/pSTAT1, CD163/c-MAF, and CD68/c-MAF was performed on tumor samples taken at the time of diagnosis." (PMID 26335330, 2015). "Nevertheless, previous immunohistochemical studies addressing the role of macrophages in tumour microenvironment have largely relied on the use of CD68 and/or CD163 only and have considered CD163 to be a marker of M2 macrophages." (PMID 25978381, 2015). "M2 macrophages highly express CD163 and CD204, and their number is positively correlated with the degree of tumor malignancy, playing a role in promoting tumor growth." (PMID 25483261, 2015). "Expression of leukocyte antigens, like CD45, CD163 and DAP12, on tumor cells has been considered as a putative proof for, e.g., macrophage × cancer cell hybrids." (PMID 26703575, 2015). "The importance of the percentage of M2 macrophages of the total macrophage count (i.e. the CD163/CD68 ratio) and M1/M2 ratio has been found in other tumor types recently, such as melanoma, non-small cell lung carcinoma and angioimmunoblastic T-cell lymphoma." (PMID 25192022, 2014). "The correlation of CD163 with VEGF expression and MVD suggests the role of CD163-positive cells in tumor angiogenesis of cHL." (PMID 24489836, 2014). "In analogy to the findings in tumor free lymph nodes a significantly decreased CD11c/CD68 and a significantly increased CD163/CD11c and MRC1/CD11c ratio was detected in the L1 cases compared to the L0 cases." (PMID 25042135, 2014). "To assess the correlation between the expression of TAM and CSC markers in human OSCCs, we stained the tumor sections from human tissue arrays for OSCC with antibodies for CD68, CD163, SOX2, ALDH1, and CD44 and compared them with normal oral mucosa samples." (PMID 24883329, 2014). "Tumor free (n = 37) and metastatic (n = 17) lymph nodes of T1 and T2 oscc patients were processed for immunohistochemistry to detect CD68, CD11c, CD163 and MRC1 positive cells." (PMID 25042135, 2014).
tumor (continued). "The relationship between TAMs and Bmi1 expression was analyzed by immunohistochemistry and quantitative real-time PCR (qRT-PCR), and results showed a positive correlation with tumor-infiltrating macrophages (CD68 and CD163) and Bmi1 expression in cancer cells." (PMID 24312366, 2013). "The average densities of CD163 and CD68 staining were 0.023±0.034 and 0.011±0.023 in tumor, respectively, and 0.037±0.040 and 0.020±0.020 in peritumoral liver tissue, respectively." (PMID 23555776, 2013). "High CD163+ and CD204+ cell counts in perivascular areas of the tumor invasive front correlate with lymphangiogensis, high tumor micro-vessel density, LNs occult metastasis and poor prognosis in PDAC patients." (PMID 23950747, 2013). "A strong inverse correlation to tumor stage was found for both NOS2 (P<0.0001) and CD163 (P<0.0001) infiltration." (PMID 23077543, 2012). "It was clear that cells other than macrophages expressed CD163, VEGF, HLA-DR, iNOS, and MRP 8/14 in both the NSCLC tumour islets and stroma." (PMID 21799753, 2011). "Immunohistochemical quantification (score 0-3) was performed for CD3, CD4, CD8, CD45RO, CD68, CD163, FoxP3, GranzymeB, iNOS, mast cell tryptase, MUM1, PD1 and TIA-1 tumor-infiltrating (TILs) reactive cells." (PMID 21179245, 2010). "We used two different markers to identify tumor-infiltrating macrophages: CD68 as a less specific lysosomal marker and CD163 as a marker more specific for macrophages." (PMID 18047662, 2007). "For example, the number of M2 TAMs, predominantly CD163+, increases in the TIM as tumor advances." (PMID 41438574, 2026). "Additionally, mIHC staining revealed an increase in M2-type TAMs positive for CD163 and CD68 within the tumor regions, whereas CD206 was poorly expressed, indicating that CD163 was a better marker in this scenario." (PMID 41545340, 2026). "However, several cancer-specific investigations observed an in vitro tumour microenvironment phenomenon where DC2s shifted towards a DC3 like-phenotype, acquiring CD14 and CD163 expression, in response to tumour-derived factors including IL-6 and M-CSF." (PMID 39861894, 2025). "They showed that high TGFB2 mRNA levels were associated with an immunologically “cold” tumor microenvironment (TME), characterized by low expression of antigen-presenting cell (APC) markers (e.g., CD14, CD163, ITGAX/CD11c), which impairs anti-tumor immune responses." (PMID 41373732, 2025). "The correlation between CD163+ cells and CD8+ (r = 0.395) may indicate the relationship between innate and adaptive immunity reactions during tumor evolution." (PMID 39936166, 2025). "Based on functional differences, TAMs can be divided into two phenotypes: M1-type TAMs (marked by CD86, iNOS, and CD169), which secrete pro-inflammatory cytokines to enhance anti-tumor immunity; and M2-type TAMs (marked by CD206, CD163, and CD204), which promote tumor invasion and immune evasion." (PMID 41320762, 2025). "Collectively, these data indicate that CD163+ TAMs are abundant in TNBC and may significantly contribute to tumor aggressiveness and adverse prognosis." (PMID 40083697, 2025). "Our study showed that in cases with high serum IL-6 levels, IL-6 uptake into the tumor is similarly enhanced within TME, and the CD8/CD163 cell ratio in the tumor is reduced, which may present an immunosuppressive microenvironment." (PMID 39652104, 2025). "We observed a significant association between high expression of the M2 macrophage marker CD163 in the tumor stroma and negative hormone receptors, which is in accordance with previous findings." (PMID 40510346, 2025). "In this study, tumor-conditioned medium derived from PC-3 cells induced M2 macrophage polarization, as evidenced by increased expression of M2 phenotype markers such as Arg1, CD206, and CD163." (PMID 41019043, 2025).